ATP6V0A4 (ATPase H+ transporting V0 subunit a4)
Description:
Subunit of the V0 complex of vacuolar(H+)-ATPase (V-ATPase), a multisubunit enzyme composed of a peripheral complex (V1) that hydrolyzes ATP and a membrane integral complex (V0) that translocates protons (By similarity). V-ATPase is responsible for acidifying and maintaining the pH of intracellular compartments and in some cell types, is targeted to the plasma membrane, where it is responsible for acidifying the extracellular environment (By similarity). Involved in normal vectorial acid transport into the urine by the kidney.
Synonyms: ATP6N1B; ATP6N2; RDRTA2; VPP2; RTADR; a4; Vph1; Stv1; DRTA3; RTA1C
Tractability: Small molecule: a structure with a bound ligand is known. Antibody: UniProt places it where antibodies can reach, with high confidence; its Gene Ontology location is reachable by antibodies, with high confidence; UniProt predicts a signal peptide or a membrane-spanning region. PROTAC: ubiquitination databases record sites on it.
Gene: Protein-coding gene on chromosome 7 (138,706,289 to 138,799,672, reverse strand). Ensembl gene ENSG00000105929.
Subcellular location: Apical cell membrane; Basolateral cell membrane
Subcellular location (Human Protein Atlas): Cytosol
Pathways (Reactome):
Transport of small molecules: Ion channel transport; Transferrin endocytosis and recycling
Immune System: ROS and RNS production in phagocytes
Signal Transduction: Insulin receptor recycling
Gene Ontology:
Molecular function: ATPase binding; protein binding; proton-transporting ATPase activity, rotational mechanism
Biological process: ossification; proton transmembrane transport; regulation of pH; renal tubular secretion; sensory perception of sound; intracellular pH reduction; vacuolar acidification; synaptic vesicle lumen acidification
Cellular component: apical part of cell; apical plasma membrane; brush border membrane; extracellular exosome; lysosomal membrane; plasma membrane; vacuolar proton-transporting V-type ATPase complex; basolateral plasma membrane; endosome; endosome membrane; phagocytic vesicle membrane; proton-transporting V-type ATPase complex; brush border; proton-transporting V-type ATPase, V0 domain; synaptic vesicle membrane; vacuolar proton-transporting V-type ATPase, V0 domain
Genetic constraint (gnomAD): Loss-of-function variants: 85 observed, 111.17 expected, observed/expected ratio (o/e) 0.76, 90% interval 0.64 to 0.92. The upper end of that interval is the gene's LOEUF score, 0.92, which puts it in group 3 of 6, group 1 being the genes least tolerant of losing a copy. Missense variants: 895 observed, 1,087.9 expected, observed/expected ratio (o/e) 0.82, 90% interval 0.78 to 0.87. Synonymous variants: 352 observed, 398.71 expected, observed/expected ratio (o/e) 0.88, 90% interval 0.81 to 0.96.
Homologues: Orthologues: chimpanzee ATP6V0A4 (99% identical), macaque ATP6V0A4 (98% identical), dog ATP6V0A4 (91% identical), guinea pig ATP6V0A4 (88% identical), rabbit ATP6V0A4 (87% identical), mouse Atp6v0a4 (85% identical), rat Atp6v0a4 (85% identical), tropical clawed frog atp6v0a4 (76% identical), pig ATP6V0A4 (61% identical), zebrafish si:ch73-173p19.2 (50% identical). Paralogues in human: ATP6V0A1 (62% identical), ATP6V0A2 (52% identical), TCIRG1 (47% identical).
Diseases named in the same sentence as ATP6V0A4 in open-access papers:
ATP6V0A4 is named in the same sentence as 31 diseases in open-access papers, as found by Europe PMC text mining. Sharing a sentence is not in itself a finding about the gene and the disease. The quoted sentences say what the papers report.
distal renal tubular acidosis (11 papers, 2012 to 2025). A kidney disorder of impaired net acid secretion by the distal tubule characterized by hyperchloremic metabolic acidosis. "ATP6V0A4 was identified as an early causative gene of distal renal tubular acidosis (dRTA) along with the gene encoding subunit B1, ATP6V1B1." (PMID 37465367, 2023). "ATP6V1B1 and ATP6V0A4 are the major pathogenic genes related to distal renal tubular acidosis (dRTA), a hereditary disease distinguished by metabolic acidosis, severe hyperchloremia, impaired bone growth and SNHL." (PMID 30686976, 2018). "Hereditary distal renal tubular acidosis (dRTA) is caused by mutations of genes encoding subunits of the H+-ATPase (ATP6V0A4 and ATP6V1B1) expressed in α-intercalated cells of the distal renal tubule and in the cochlea." (PMID 22966473, 2012). "At that time, distal renal tubular acidosis was diagnosed and next-generation sequencing (NGS) identified an autosomal recessively inherited, pathogenic, homozygous mutation in exon 12 of the ATP6V0A4 gene (NM_130841.2, c.1215C > G, p.F405L)." (PMID 39915375, 2025). "Pathogenic variants in the B1 and a4 subunits of H+-ATPase (ATP6V1B1, ATP6V0A4) and in AE1 (SLC4A1) have been identified as the cause of distal renal tubular acidosis (dRTA) almost two decades ago." (PMID 38448728, 2024). "Hereditary distal renal tubular acidosis (dRTA) is a rare disease of H+ excretion defect of α-intercalated cells in renal collecting duct, caused by decreased V-ATPase function due to mutations in the ATP6V1B1 or ATP6V0A4 genes." (PMID 32123165, 2020).
hearing loss (4 papers, 2012 to 2025). "A patient with a homozygous mutation in the ATP6V0A4 gene (deletion of exons 3–5) was monitored until the age of 11, at which point it was observed that the child exhibited hearing impairment, aligning with the characteristics associated with advanced sensorineural deafness." (PMID 41395315, 2025). "In addition to sensorineural hearing loss, the long-term consequences of primary dRTA resulting from variations in the ATP6V0A4 gene also encompass growth retardation, renal impairment, and kidney failure." (PMID 41395315, 2025).
sensorineural hearing loss (4 papers, 2013 to 2025). "For example, RTA had been reported to be related to the SLC4A1, ATP6V1B1 and ATP6V0A4 genes, and mutations in ATP6V1B1 and ATP6V0A4 genes were predisposed to causing sensorineural hearing loss in children." (PMID 41311422, 2025). "In comparison, ATP6V1B1 and ATP6V0A4 genes have only AR genetic pattern, which is more likely to be combined with sensorineural hearing loss (SNHL)." (PMID 35612621, 2022). "The recessive form of the disease (which is usually associated with sensorineural deafness) is attributable to mutations in ATP6V1B1 or ATP6V0A4, which encode the tissue-restricted B1 and a4 subunits of the renal apical H+-ATPase." (PMID 26068435, 2015). "We aim to identify molecular defects present in the ATP6V1B1, ATP6V0A4 and SLC4A1 genes in a Tunisian cohort, according to the following algorithm: first, ATP6V1B1 gene analysis in dRTA patients with sensorineural hearing loss (SNHL) or unknown hearing status." (PMID 24252324, 2013).
deafness (3 papers, 2009 to 2022). An inherited or acquired condition characterized by the complete loss of the ability to hear from one or both ears. "In 1999, renal tubular acidosis with deafness was the first phenotype linked to the V-ATPase with mutations in the kidney-specific isoforms ATP6V1B1 (MIM 267300) or ATP6V0A4 (MIM 602722) (refs 3, 4, 5)." (PMID 27231034, 2016). "These include deafness as reported in family 1, and also reported for ATP6V0A4 and ATP6V1B1 defects." (PMID 27231034, 2016). "Additionally, there are genetic variants associated with deafness or late-onset deafness (e.g., ATP6V1B1 and ATP6V0A4)." (PMID 35346296, 2022).
renal tubular acidosis (3 papers, 2015 to 2025). A group of genetic disorders of the kidney tubules characterized by the accumulation of metabolically produced acids with elevated plasma chloride, hyperchloremic metabolic acidosis. "This case expands the known mutational and phenotypic spectrum of ATP6V0A4-related renal tubular acidosis." (PMID 41395315, 2025). "Although ATP6V0A4 has been linked to renal tubular acidosis, none of the specific SNPs indicated are implicated in the disease." (PMID 30619461, 2018).
glioma (2 papers, 2018 to 2023). A benign or malignant brain and spinal cord tumor that arises from glial cells (astrocytes, oligodendrocytes, ependymal cells). "Notably, ATP6V0A4, a constituent of the v-ATPases ensemble, has been documented to manifest pronouncedly in breast cancer and gliomas." (PMID 38075693, 2023). "ATP6V0A4 is one subunit of v-ATPase which was reported to be involved in chemo-resistance and invasion of tumor cells and a biomarker for specific subtypes of human gliomas." (PMID 30355311, 2018).
Hypokalemia (2 papers, 2019 to 2025). An abnormally decreased potassium concentration in the blood. "Here, we report a family diagnosed with hypochloremic metabolic alkalosis, acidic urine, and hypokalemia, who carry a missense variant c.1534G>T (p.Val512Leu) in the ATP6V0A4 gene." (PMID 40299568, 2025).
calcium oxalate kidney stone (1 paper, 2022). "Mutations in ATP6V1B1 and ATP6V0A4 have been identified in calcium oxalate kidney stone patients, suggesting that they are essential for calcium oxalate kidney stone formation." (PMID 35696569, 2022).
epilepsy (1 paper, 2023). A brain disorder characterized by episodes of abnormally increased neuronal discharge resulting in transient episodes of sensory or motor neurological dysfunction, or psychic dysfunction. "The top pathway associated with ATP6V0A4 (increased by 4.2-fold in AD and by 2.6-fold in epilepsy compared to controls) from the increased proteins in the correlation was the iron homeostasis signaling pathway (p = 3.80 x 10−4)." (PMID 37521285, 2023).
focal segmental glomerulosclerosis (1 paper, 2025). A renal disorder characterized by sclerotic lesions in the glomeruli. "IHC and immunofluorescence analyses of renal biopsies from the proband and other patients indicated that the proband had higher renal tubular ATP6V0A4 protein expression abundance compared with patients with minimal change nephropathy, IgA nephropathy, or focal segmental glomerulosclerosis." (PMID 40299568, 2025).
nephrolithiasis (1 paper, 2022). The presence of a calculus in the pelvis of the kidney; this is most often composed of mineral salts and proteins. "Finally, the fly orthologs of two genes associated with nephrolithiasis, ATPase H+ Transporting V1 Subunit B1 (ATP6V1B1) and ATP6V0A4 (Vacuolar H+-ATPase 55kD subunit [Vha55] and Vha100-2 in flies), are highly expressed in Malpighian tubule principal cells." (PMID 35696569, 2022).
oncocytoma (1 paper, 2017). "The chRCC and oncocytoma samples displayed almost identical gene expression profiles for MAL, TMEM255A, RHCG, ATP6V0A4, STAP1, and DEFB1, as demonstrated by both RNA microarray and RNA sequencing, which is in agreement with the known fact that chRCC and oncocytoma are related neoplasms." (PMID 29208006, 2017).
tumor (8 papers, 2013 to 2026). "Interestingly, the results observed that 5 hub genes were shared in the GEO and TCGA profiles, including SLC44A3, DBF4, NAPSA, ATP6V0A4, and CLDN4, which were closely associated with B cells, CD4+ T cells, CD8+ T cells, Macrophage, Neutrophil, and Dendritic cells to involve in tumor immunity." (PMID 36325324, 2022). "The identified gene expression signature included 14 genes, five (CDYL, ATP6V0A4, PREP, RTN41P1, BEND3 and Kif18A) of which were up-regulated in the group of primary tumours of the patients with visceral organ metastasis." (PMID 30961553, 2019). "In fact, SULF2 is involved in Wnt-driven tumor progression, PLAUR in extracellular matrix remodeling and migration, DUSP4 in sustaining epithelial–mesenchymal plasticity, and ATP6V0A4/V-ATPase-dependent acidification in invasive phenotypes." (PMID 41596301, 2026).
kidney diseases (2 papers, 2023 to 2024). "Consistent with the gene expression of ferroptosis, dysregulation of CD163, PC, and ATP6V0A4 was specific in the glomerular compartment of patients with LN from the GSE104948 cohort compared to other kidney diseases (especially FSGS, MCD, and MGN)." (PMID 37583695, 2023).
ATP6V0A4 also shares sentences with these, for which no sentence is quoted: Hearing impairment (2 papers); breast carcinoma (1); cyst (1); glaucoma (1); IgA nephropathy (1); invasive carcinoma (1); kidney failure (1); leukemia (1); metastatic disease (1); minimal change nephropathy (1); nephrocalcinosis (1); Nephropathy (1); pancreatitis (1); papillary thyroid carcinoma (1); Pseudoxanthoma elasticum (1); Sepsis (1); staphylococcus aureus infection (1).